CYP26C1 (cytochrome P450 family 26 subfamily C member 1)
Description:
A cytochrome P450 monooxygenase involved in the metabolism of retinoates (RAs), the active metabolites of vitamin A, and critical signaling molecules in animals. RAs exist as at least four different isomers: all-trans-RA (atRA), 9-cis-RA, 13-cis-RA, and 9,13-dicis-RA, where atRA is considered to be the biologically active isomer, although 9-cis-RA and 13-cis-RA also have activity (Probable). Catalyzes the oxidation of atRA primarily at C-4. Oxidation of atRA limits its biological activity and initiates a degradative process leading to its eventual elimination, thereby contributes to the regulation of atRA homeostasis and signaling (Probable). Able to metabolize other RAs such as 9-cis with high efficiency. Can oxidize all-trans-13,14-dihydroretinoate (DRA) to metabolites which could include all-trans-4-oxo-DRA, all-trans-4-hydroxy-DRA, all-trans-5,8-epoxy-DRA, and all-trans-18-hydroxy-DRA (By similarity). Shares sequence similarity with other CYP26 family members, but has higher affinity to 9-cis-RA and is much less sensitive to the inhibitory effects of ketoconazole. In cooperation with Cyp26a1, contributes to the CNS patterning and the development of regions of higher visual acuity (By similarity).
Synonyms: FFDD4
Tractability: Small molecule: it belongs to a druggable protein family. Antibody: UniProt predicts a signal peptide or a membrane-spanning region. PROTAC: ubiquitination databases record sites on it.
Gene: Protein-coding gene on chromosome 10 (93,060,798 to 93,069,540, forward strand). Ensembl gene ENSG00000187553.
Subcellular location: Membrane
Pathways (Reactome):
Disease: Defective CYP26C1 causes FFDD4
Metabolism: Vitamins
Signal Transduction: RA biosynthesis pathway
Gene Ontology:
Molecular function: retinoic acid 4-hydroxylase activity; retinoic acid binding; heme binding; iron ion binding; monooxygenase activity; oxidoreductase activity, acting on paired donors, with incorporation or reduction of molecular oxygen; oxidoreductase activity, acting on paired donors, with incorporation or reduction of molecular oxygen, reduced flavin or flavoprotein as one donor, and incorporation of one atom of oxygen
Biological process: retinoic acid catabolic process; anterior/posterior pattern specification; central nervous system development; negative regulation of retinoic acid receptor signaling pathway; neural crest cell development; organelle fusion; vitamin metabolic process
Cellular component: endoplasmic reticulum membrane; membrane
Genetic constraint (gnomAD): Loss-of-function variants: 44 observed, 30.72 expected, observed/expected ratio (o/e) 1.43, 90% interval 1.12 to 1.82. The synonymous counts are far from expectation, so gnomAD's model fits this gene poorly and the ratio says little. Missense variants: 802 observed, 583.03 expected, observed/expected ratio (o/e) 1.38, 90% interval 1.3 to 1.46. Synonymous variants: 354 observed, 262 expected, observed/expected ratio (o/e) 1.35, 90% interval 1.24 to 1.48.
Homologues: Orthologues: chimpanzee CYP26C1 (99% identical), macaque CYP26C1 (97% identical), dog CYP26C1 (92% identical), rabbit CYP26C1 (92% identical), pig CYP26C1 (90% identical), guinea pig CYP26C1 (87% identical), mouse Cyp26c1 (87% identical), rat Cyp26c1 (86% identical), tropical clawed frog cyp26c1 (65% identical), zebrafish cyp26c1 (57% identical). Paralogues in human: CYP26B1 (52% identical), CYP26A1 (43% identical).
Diseases named in the same sentence as CYP26C1 in open-access papers:
CYP26C1 is named in the same sentence as 11 diseases in open-access papers, as found by Europe PMC text mining. Sharing a sentence is not in itself a finding about the gene and the disease. The quoted sentences say what the papers report.
Blindness (1 paper, 2025). Blindness is the condition of lacking visual perception defined as a profound reduction in visual perception. "Interestingly, deletions involving the 5' portion of the EXOC6A gene and two adjacent cytochrome p450 genes (CYP26A1 and CYP26C1) are associated with autosomal-dominant nonsyndromic optic aplasia (ONA), an extremely rare disorder that causes unilateral or bilateral blindness in the affected eye." (PMID 40777261, 2025).
cholangiocarcinoma (1 paper, 2023). A carcinoma that arises from the intrahepatic biliary tree (intrahepatic cholangiocarcinoma) or from the junction, or adjacent to the junction, of the right and left hepatic ducts (hilar cholangiocarcinoma). "A cfDNA analysis of cholangiocarcinoma patients and healthy sex- and age-matched controls revealed differentially methylated regions (DMRs) in four genes (HOXA1, PRKCB, CYP26C1, and PTGDR) in CCA patients." (PMID 37568696, 2023).
colorectal cancer (1 paper, 2014). A primary or metastatic malignant neoplasm that affects the colon or rectum. "This study has defined the expression profile of the retinoic acid metabolising enzymes CYP26A1, CYP26B1 and CYP26C1 which are members of the P450 family of enzymes and LRAT in a large cohort of well characterised colorectal cancers." (PMID 24608339, 2014).
diabetes (1 paper, 2023). "However, our data show that Tbx1 expression in mouse embryos did not alter under maternal diabetes with or without PHZ treatment, which are in line with the findings of unchanged Cyp26b1 and Cyp26c1 expressions in diabetic pregnancy." (PMID 37616226, 2023).
ischemic stroke (1 paper, 2021). A stroke disorder caused by obstruction of blood flow to the brain, due to thrombotic (local blood clot formation) or embolic (due to a blood clot or other material traveling from another site) event. "Until now, the effect of CYP26C1 on stroke has not been fully understood, but several studies into the effects of RA in ischemic stroke have provided indirect evidence that CYP26C1 might be associated with ischemic stroke." (PMID 34681016, 2021).
Kaufman Oculocerebrofacial Syndrome (1 paper, 2020). "Finally, deletions of CYP26A1 (MIM 602239) and CYP26C1 (MIM 608428) have previously been implicated in both nonsyndromic bilateral and unilateral optic nerve aplasia, and mutations in UBE3B (MIM 608047) have been described in Kaufman Oculocerebrofacial Syndrome (MIM 244450)." (PMID 32040484, 2020).
schizophrenia (1 paper, 2013). A major psychotic disorder characterized by abnormalities in the perception or expression of reality. "Seven genes were investigated and involved in the synthesis, degradation and transportation of RA, ALDH1A1, ALDH1A2, ALDH1A3, CYP26A1, CYP26B1, CYP26C1 and Transthyretin (TTR), for their roles in the development of schizophrenia." (PMID 24564241, 2013).
Stroke (1 paper, 2021). Sudden impairment of blood flow to a part of the brain due to occlusion or rupture of an artery to the brain. "Because CYP26C1 catalyzes the degradation of all-trans RA, these studies suggest the hypothesis that variation in CYP26C1 activity and epigenetic chromosomal changes in CYP26C1, which affect the mRNA expression of CYP26C1, might be associated with stroke." (PMID 34681016, 2021). "Until now, the relation between CYP26C1 and stroke has not been understood, but some important studies into RA and stroke suggest that the function of CYP26C1 might be affected by stroke, leading to poor outcomes." (PMID 34681016, 2021).
cancer (2 papers, 2019). A tumor composed of atypical neoplastic, often pleomorphic cells that invade other tissues. "The risk of developing oral malignant disorders may be related to the functionally relevant combined effects of SNPs such as those in CYP26A1, CYP26B1, and CYP26C1 within and between different cancer pathways." (PMID 31465460, 2019). "Additionally, CYP26C1 in the path:00830_3 is involved in the metabolic breakdown of retinoic acid, which could be more effective in the growth inhibition of cancer cells." (PMID 31156704, 2019).
of the skin (1 paper, 2016). "Homozygous/compound heterozygous mutations in CYP26C1 have previously been associated with focal facial dermal dysplasia type IV, a mild disorder of the skin." (PMID 27861128, 2016).
CYP26C1 also shares sentences with these, for which no sentence is quoted: infection (1 paper).